SYNJ2 (synaptojanin 2)
Diseases named in the same sentence as SYNJ2 in open-access papers:
SYNJ2 is named in the same sentence as 51 diseases in open-access papers, as found by Europe PMC text mining. Sharing a sentence is not in itself a finding about the gene and the disease. The quoted sentences say what the papers report.
breast carcinoma (8 papers, 2018 to 2024). "For example, SYNJ2, which encodes the 5’-inositol lipid phosphatase, synaptojanin 2, has been reported to promote cell migration and invasion in breast cancer and is associated with a high risk of colorectal cancer." (PMID 34680938, 2021). "For example, the increase in SYNJ2 in breast cancer promotes the recycling of EGFR, stimulating cell movement and tumor formation." (PMID 36899380, 2023). "Overexpressed SYNJ2 boosts the invasion and migration of glioma and breast cancer cells and prompts poor prognosis for cancer patients." (PMID 35581615, 2022). "In breast cancer, overexpression or amplification of SYNJ2 was considered to be closely correlated with shorter survival times." (PMID 33641617, 2021). "Similar to SHIP2, synaptojanin 2 (SYNJ2) has been identified as a putative oncogene in breast cancer." (PMID 33276499, 2020). "Although very few studies have investigated the role SYNJ2 plays in regulating breast cancer, one reported that copy number gain, or increased expression of SYNJ2 in a small cohort of breast cancer patients correlated with shorter survival in ER+ tumours." (PMID 33276499, 2020). "For example, copy number gain of SYNJ2 in breast cancer leads to EGFR activation by altered trafficking pathways." (PMID 31073965, 2019). "Genetic variation in SYNJ2 is widely found in human diseases, such as reduced cognitive ability, Alzheimer’s disease and depression, medulloblastoma, colorectal cancer, prostate cancer, hairy cell leukemia, glioma, and breast cancer." (PMID 35581615, 2022). "Hereinto, SYNJ2 plays a critical role in glioma and breast cancer metastasis." (PMID 35581615, 2022). "Moreover, homozygous deletion of SYNJ2 was detected in prostate cancer cells, and increases in SYNJ2 copies induced decreased breast cancer patient survival." (PMID 33641617, 2021). "Similar to SHIP2, SYNJ2 also plays a role in regulating EGFR turnover in breast cancer cells." (PMID 33276499, 2020). "However, paradoxically, increased expression of the lipid phosphatases SHIP2 and SYNJ2 can have pro-tumourigenic effects in breast cancer, indicating more diverse roles for the 5-phosphatases." (PMID 33276499, 2020). "This review will discuss how PTEN, PIPP, SHIP2 and SYNJ2 distinctly regulate multiple functional targets, and the mechanisms by which dysregulation of these distinct phosphoinositide phosphatases differentially affect breast cancer progression." (PMID 33276499, 2020). "In addition to genomic loss, PTEN missense and nonsense mutations occur in 5.49% of breast cancers, whereas mutations in the 5-phosphatases are less common: PIPP 0.62%, SHIP2 1.79% and SYNJ2 3.6% of breast cancers (COSMIC database, cancer.sanger.ac.uk)." (PMID 33276499, 2020). "Interestingly, while PTEN is a bona fide tumour suppressor and is frequently mutated/lost in breast cancer, 5-phosphatases such as PIPP, SHIP2 and SYNJ2, have demonstrated more diverse roles in regulating mammary tumourigenesis." (PMID 33276499, 2020). "Synj2-null or transgenic overexpressing mice have also not yet been reported and warrant further investigation in the context of breast cancer to determine whether SYNJ2 is oncogenic in vivo." (PMID 33276499, 2020). "SYNJ2 may also mediate breast cancer cell invasion and metastasis through its role in promoting invadopodia formation." (PMID 33276499, 2020). "Furthermore, small compound inhibition of SYNJ2 decreased the invasive ability of MDA-MB-231 cells, without inhibiting the related protein SYNJ1, suggesting that SYNJ2 may be a potential druggable target to block breast cancer metastasis." (PMID 33276499, 2020). "According to previous studies, high expression of SYNJ2 was correlated with hepatocellular tumorigenesis via the CTCF/POLR2A-SYNJ2 axis and with metastasis of glioma and breast cancer through regulating the formation of lamellipodia and invadopodia." (PMID 35581615, 2022).
breast carcinoma (continued). "As SHIP2 and SYNJ2 both contribute to EGFR turnover, future studies should investigate whether PIPP also regulates receptor trafficking, as another mechanism by which this 5-phosphatase differentially regulates breast cancer progression, especially as PIPP is also recruited to membrane ruffles." (PMID 33276499, 2020).
hearing loss (8 papers, 2011 to 2024). "We also identified rare coding associations in fascin actin-bundling protein 2 (FSCN2) and synaptojanin 2 (SYNJ2) with increased risk for hearing loss, both of which were recently observed in UKB18." (PMID 35661827, 2022). "As progressive hearing loss is so common in the human population, starting at any age, the human orthologue SYNJ2 is a good candidate for involvement in human hearing loss." (PMID 33100973, 2020). "To investigate the mechanisms underlying progressive hearing loss, we have studied a different mutation of Synj2 to look for any evidence of involvement of vesicle trafficking particularly affecting the synapses of sensory hair cells." (PMID 33100973, 2020). "Analysis of human DNA samples to determine if mutations in the SYNJ2 gene cause hearing loss in humans is in progress." (PMID 21423608, 2011). "Although no members of the Synaptojanin family have been associated with hearing loss in humans, mutations that abolish the lipid phosphatase activity of Synaptojanin 2 result in progressive age-related hearing loss in mice without any other accompanying phenotype." (PMID 30258843, 2018). "The genes ARHGEF28, SYNJ2, and ACAN have been previously implicated in common variant studies of hearing loss (GWAS)." (PMID 38943082, 2024). "Associations linked to SYNJ2 and GRM5 point towards the cochlear conductance of auditory signals to play a role in hearing loss risk." (PMID 34847940, 2021). "An additional five genes have not previously been associated with human hearing loss but are known to cause hearing loss or cochlear development when mutated in mice: SYNJ2, RPGRIP1L, BAIAP2L2, TUB, and RBL2." (PMID 32986727, 2020).
colorectal cancer (3 papers, 2021 to 2022). A primary or metastatic malignant neoplasm that affects the colon or rectum. "In colorectal cancer, an increased protein level of SYNJ2 was reported, and the SYNJ2 variant rs9365723 was taken to be a risk factor in Chinese patients." (PMID 33641617, 2021). "With genetic changes, SYNJ2 triggers colorectal cancer, medulloblastoma, prostate cancer, and hepatocellular carcinoma." (PMID 35581615, 2022). "SYNJ2 probably plays a key role in the tumorigenesis of colorectal cancer." (PMID 33641617, 2021).
deafness (3 papers, 2011 to 2022). An inherited or acquired condition characterized by the complete loss of the ability to hear from one or both ears. "As Synj2 mutant mice exhibit deafness, in situ hybridization was performed to determine the site of Synj2 expression within the cochlea." (PMID 21423608, 2011). "In one of our strains, Mozart, we have identified the causative mutation to be in the Synj2 gene, which has not previously been associated with deafness." (PMID 21423608, 2011).
Alzheimer disease (2 papers, 2022 to 2025). A progressive, neurodegenerative disease characterized by loss of function and death of nerve cells in several areas of the brain leading to loss of cognitive function such as memory and language. "Dysregulation of SYNJ2 has been implicated in several neurodevelopmental and neurodegenerative disorders, including Alzheimer’s disease, Parkinson’s disease, and autism spectrum disorder, conditions often associated with synaptic dysfunction, chronic inflammation, and impaired plasticity." (PMID 40646790, 2025). "Synaptojanin 2 (SYNJ2) was reported as a cell-type-specific methylation biomarker associated with aging, especially in neuronal diseases, such as Alzheimer's disease and progressive hearing loss." (PMID 35845072, 2022).
atherosclerosis (2 papers, 2017 to 2022). A disease characterized by the build-up of fatty material and calcium deposition in the arterial wall resulting in partial or complete occlusion of the arterial lumen. "LCP2, EIF4EBP1, HCK, and PPP4C were demonstrated to be highly expressed, and SYNJ2 was demonstrated to be lowly expressed in atherosclerosis compared to the control group, which can be diagnostic biomarkers for patients with atherosclerosis." (PMID 35845072, 2022). "LCP2, EIF4EBP1, HCK, and PPP4C were demonstrated to be highly expressed and SYNJ2 was demonstrated to be lowly expressed in the atherosclerosis mice model." (PMID 35845072, 2022).
glioblastoma (2 papers, 2021 to 2022). The most malignant astrocytic tumor (WHO grade IV). "INPP5B and SYNJ2 are from the same gene family and could potentially control the motility of glioblastoma cells." (PMID 33641617, 2021).
lung carcinoma (2 papers, 2022 to 2023). "In terms of lung cancer, only one study showed the relationship between SYNJ2 and lung cancer; after studying 1404 lung cancer patients, it revealed that people with high SYNJ2 transcript levels are prone to shorter survival times." (PMID 35581615, 2022). "Next to it, Synaptojanin 2 (SYNJ2) was shown to be a good marker of poor prognosis in lung cancer." (PMID 37895091, 2023).
asthma (1 paper, 2021). "Among these genes, most have been associated with immune response or asthma, such as HNMT, SYNJ2, or CST7." (PMID 34834492, 2021).
breast tumours (1 paper, 2020). "Paradoxically, SHIP2 and SYNJ2 are increased in primary breast tumours, which correlates with invasive disease and reduced survival." (PMID 33276499, 2020).
esophageal carcinoma (1 paper, 2022). A primary or metastatic malignant neoplasm involving the esophagus. "Moreover, the expression level of SYNJ2 was positively associated with TMB in ACC, esophageal carcinoma (ESCA), LUAD, and STAD; it was negatively related to TMB in KIRC, KIRP, LGG, and THCA." (PMID 35581615, 2022).
lung squamous cell carcinoma (1 paper, 2022). "The roles and clinical values of synaptojanin 2 (SYNJ2) in lung squamous cell carcinoma (LUSC) remain unclear." (PMID 35581615, 2022).
lymph node metastases (1 paper, 2022). "Second, most of the in-house cases included in our study were at an early stage, did not have distant and lymph node metastases, and lacked clinical follow-up information, which limited our capacity to gain a comprehensive understanding of the clinical significance of SYNJ2 in LUSC." (PMID 35581615, 2022).
ovarian serous cystadenocarcinoma (1 paper, 2022). A malignant serous cystic epithelial neoplasm arising from the ovary. "In three cancers—KICH, OV (ovarian serous cystadenocarcinoma), and PCPG, SYNJ2 were found related to at least five KEGG signaling pathways." (PMID 35581615, 2022).
prostate adenocarcinoma (1 paper, 2022). "For MSI, SYNJ2 expression was positively relevant to LUSC, sarcoma (SARC), and testicular germ cell tumors (TGCT) and negatively associated with MSI in BRCA, DLBC (lymphoid neoplasm diffuse large B-cell lymphoma), HNSCC and prostate adenocarcinoma (PRAD)." (PMID 35581615, 2022).
tumor (7 papers, 2017 to 2025). "SYNJ2 expression is also associated with invasive disease, high tumour grade, cell proliferation and overexpression of HER2." (PMID 33276499, 2020). "The immune response plays an essential role in anti-tumor, and thus the immune relevance of SYNJ2 in pan-cancer was investigated in this study." (PMID 35581615, 2022). "In various types of tumor cells, SYNJ2 has been found to play an essential role in invasiveness capability." (PMID 33641617, 2021). "The clathrin-mediated endocytosis and formation of invadopodia mediated by SYNJ2 are considered to be closely related to the invasive behavior of tumor cells." (PMID 33641617, 2021). "SYNJ2 depleted MDA-MB-231 cells exhibited a reduced ability to form tumours in xenograft models, which was restored upon re-expression of wild-type, but not catalytically-deficient mutant SYNJ2." (PMID 33276499, 2020). "Previous studies have reported that SYNJ2 is responsible for tumor initiation and progression." (PMID 35581615, 2022). "In anaplastic intracranial ependymomas, deletion within the SYNJ2 loci may inhibit tumor invasion and may be a marker of good prognosis." (PMID 33641617, 2021). "The removal of tumor suppressor genes sorting nexin 9 (SNX9) and synaptojanin 2 (SYNJ2) in the 6q25.3 location of chromosome 6 disturbs their functions, including the regulation of cell migration from the primary tumor site to distant organs and the inhibition of tumor development." (PMID 34203272, 2021).
cancer (6 papers, 2017 to 2025). A tumor composed of atypical neoplastic, often pleomorphic cells that invade other tissues. "According to Cox analyses and Kaplan–Meier curves, SYNJ2 expression was associated with the prognosis of several cancers." (PMID 35581615, 2022). "This research also disclosed the close association between SYNJ2 expression and the immune environment and the potential of this gene as a novel and potential biomarker for the prediction and treatment of multiple cancers, including LUSC." (PMID 35581615, 2022). "From these results, SYNJ2 generally served as a risk marker for the prognosis of cancer patients." (PMID 35581615, 2022). "The results of sROC analysis also demonstrate high accuracy of SYNJ2 expression in identifying 20 types of cancers from their controls (AUC = 0.87)." (PMID 35581615, 2022). "Overexpressed SYNJ2 identities cancer status and predicts a poor prognosis for individuals with one type of multiple cancers, including LUSC." (PMID 35581615, 2022). "Few studies have focused on the molecular mechanistic understanding of SYNJ2 in human malignant tumors." (PMID 35581615, 2022). "The expression patterns of SYNJ2 in different cancers were various, and its clinical relevance is conspicuous." (PMID 35581615, 2022). "Further, a pan-cancer analysis based on 10,238 sapiens was performed to promote the understating of the expression and clinical significance of SYNJ2 in multiple human cancers." (PMID 35581615, 2022). "SYNJ2 expression made it feasible to differentiate cancer samples from corresponding normal samples with at least moderate accuracy (AUC > 0.75)." (PMID 35581615, 2022). "Previous studies have revealed that abnormal expression of SYNJ2 plays different roles in several cancers." (PMID 33641617, 2021). "The cancer-promoting effect of SYNJ2 may be related to protein digestion and absorption and extracellular matrix-receptor interaction." (PMID 35581615, 2022). "Distinct SYNJ2 expression levels were identified in 14 types of cancer cell lines." (PMID 35581615, 2022). "Moreover, the distinct expression levels and essential clinical relevance of SYNJ2 in a series of cancers were initially revealed in this study." (PMID 35581615, 2022). "In this study, various SYNJ2 expression was identified between 14 cancer cell lines." (PMID 35581615, 2022). "Taken together, SYNJ2 may be a novel marker for predicting cancer status and prognosis of multiple cancers." (PMID 35581615, 2022). "In addition, SYNJ2 was found related to the “DRUG METABOLISM CYTOCHROME P450” KEGG signaling pathway in several cancers (at least KICH, OV, and PCPG), indicating its druggable potential, which has also been demonstrated in BRCA before." (PMID 35581615, 2022). "SYNJ2 expression made it feasible to differentiate multiple types of cancers from their corresponding normal samples with at least moderate accuracy, suggesting its potential in identifying cancer status." (PMID 35581615, 2022). "Moreover, this study initially investigated the expression levels and clinical relevance of SYNJ2 in pan-cancer, demonstrating the novel and potential biomarker for the prediction and treatment of cancers." (PMID 35581615, 2022). "Finally, a pan-cancer analysis based on 9781 samples was also performed in this study, contributing to the understanding of SYNJ2 in multiple cancers." (PMID 35581615, 2022). "This suggests that SYNJ2 expression may coincide with phosphorylation of SYNJ2BP in cancer." (PMID 38504131, 2024). "Interestingly, “DRUG METABOLISM CYTOCHROME P450” was the overlap of three cancers, indicating that the important mechanism of SYNJ2 in various cancers may be related to this pathway." (PMID 35581615, 2022). "Additionally, formation of cellular lamellipodia and invadopodia promoted by SYNJ2 might affect the migration and invasion of cancer cells." (PMID 33641617, 2021).
cancer (continued). "This study disclosed the clinical significance of SYNJ2 in LUSC and multiple cancers, demonstrating the novel and potential biomarker for predicting and treating cancers." (PMID 35581615, 2022). "Thus, SYNJ2 was dramatically upregulated in LUSC and can predict both the cancer status and the poor prognosis for patients with LUSC, which has not been reported before, indicating the novelty of this study." (PMID 35581615, 2022).
SYNJ2 also shares sentences with these, for which no sentence is quoted: glioma (2 papers); hepatocellular carcinoma (2); Parkinson’s (2); prostate carcinoma (2); alcoholic liver diseases (1); autism spectrum disorder (1); Azoospermia (1); breast invasive carcinoma (1); cholangiocarcinoma (1); cognitive disorder (1); colon adenocarcinoma (1); depression (1); dilated cardiomyopathy (1); hemorrhage (1); infection (1); inflammatory bowel disease (1); ischemic cardiomyopathy (1); kidney chromophobe (1); lung adenocarcinoma (1); major depressive disorder (1); male infertility (1); medulloblastoma (1); mesothelioma (1); oculocerebrorenal syndrome (1); osteoporosis (1); paraganglioma (1); pheochromocytoma (1); rheumatoid arthritis (1); sarcoma (1); small cell lung carcinoma (1).
A further 4 diseases each share a sentence with SYNJ2 in 1 paper.